RAB25 (RAB25, member RAS oncogene family)
Diseases named in the same sentence as RAB25 in open-access papers (continued):
Sharing a sentence is not in itself a finding about the gene and the disease.
tumor (continued). "In the retrospective study, we performed an immunohistochemical analysis of RAB25 protein expression in 97 pretreatment tumor biopsies of locally advanced HNSCC patients, who had an average follow-up time of 68 months." (PMID 24403269, 2013). "Rab25 is a determinant of tumor progression, and the aggressiveness of epithelial cancers and is strongly associated with decreased survival." (PMID 22121362, 2012). "For example, Rab25 contributes to tumor progression by directing the localization of integrin-recycling vesicles and thereby enhancing the ability of tumor cells to invade the extracellular matrix." (PMID 22121362, 2012). "Nevertheless, RAB11FIP1 also interacts with RAB25 that can act as a tumor suppressor or tumor promoter depending on the RCP expression status." (PMID 22724020, 2012). "In the case of the adenomatous polyposis coli model ApcMin mice, breeding onto the Rab25 knockout background led to a four-fold increase in polyp number in the intestines and a two-fold increase in the tumour number in the colon." (PMID 21063400, 2011). "In immunostained tumor tissues, AD cells showed immunostaining of S100P in the cytoplasm and the nucleus, while SQ cells showed immunostaining of RAB25 in the cytoplasm." (PMID 20142997, 2010). "Reports indicate that Rab25 is involved in tumor progression by regulating the localization of integrin-recycling vesicles to enhance tumor invasion." (PMID 21143914, 2010). "Increased expression of Rab25 has also been noted in prostate cancer and transitional cell carcinoma of the bladder, indicating that it has a pathological role in tumor progression in several epithelial lineages." (PMID 21143914, 2010). "In contrast, Rab25 has also been shown to function as a tumor suppressor; its expression is lost in hormonally insensitive breast tumors." (PMID 21143914, 2010). "The expression of Rab25 correlated with histological grade, and expression was higher in endometrioid (median histoscore 10.5) than serous (7.5) or mucinous (5.3) tumours." (PMID 19623182, 2009). "Rab25 directs the localization of integrin α5β1–containing recycling vesicles/endosomes to the leading edge of migrating cells to promote the formation of long actin-rich pseudopodia and enhance the ability of tumor cells to invade the extracellular matrix." (PMID 40614209, 2025). "Tumor formation was not seen in the control group mice, suggesting that loss of RAB25 and overexpression of mutant H-RAS61L are both necessary for transformation." (PMID 38803515, 2024). "Interestingly, RAB25 plays a dual role in BC, functioning as a tumor promoter in luminal cancers, and as a tumor inhibitor in TNBC." (PMID 38533085, 2024). "Rab25 plays a tumor suppressive role in colorectal cancer and cutaneous squamous cell carcinoma." (PMID 34141705, 2021). "Rab25 can act as a tumor suppressor or tumor promoter in different tumors." (PMID 34141705, 2021). "Conversely, RAB25 levels were remarkably reduced in tumor tissues compared with the normal." (PMID 34868916, 2021). "miR-185-3p/RAB25 signaling controlled tumor progression and correlated with disease prognosis." (PMID 34868916, 2021). "To conclude, the findings demonstrate exosomal miR-185-3p promotes tumor growth by mediating RAB25 that could be effectively targeted for HNSCC treatment." (PMID 34868916, 2021). "Furthermore, the immunohistochemical analysis results showed higher Rab25, β1 integrin, β‐catenin and ki‐67 expression in tumour tissues from the PC9/Rab25 and HCC827/Rab25 groups than those observed in the PC9/vector and HCC827/vector groups." (PMID 30848009, 2019). "In addition, Rab25 expression was increased in the acquired resistance to erlotinib or gefitinib tumour samples compared to the initial specimens." (PMID 30848009, 2019). "It has been demonstrated that Rab25 enhances cell proliferation and tumor development." (PMID 28969096, 2017).
tumor (continued). "Finally, cell proliferation of MDA-MB231 cells was significantly decreased with RAB25 overexpression relative to mock cells, in agreement with previous assertions of a tumor suppressive role." (PMID 28939823, 2017). "However, an opposite effect has also been reported, in which RAB25 acts as a tumor suppressor in colon cancer." (PMID 28784136, 2017). "Rab25 enhances cell growth, cell migration/invasion, chemoresistance and in vivo tumor growth." (PMID 28969096, 2017). "The oncogenic or tumor suppressive functions of Rab25 are cell-type dependent." (PMID 27716280, 2016). "It has also been suggested that the expression status of the Rab25 effector RCP could be a determinant of the ability of Rab25 to act as a tumor promoter or suppressor." (PMID 25815277, 2015). "We show that Rab25 expression in this cell line induces cisplatin resistance in vitro and in vivo, although the in vivo resistance to treatment is also determined by the localisation of the tumour." (PMID 26384969, 2015). "Intraperitoneal injection of A2780 cells stably expressing Rab25 and luciferase resulted in tumour growth accumulation and death of all the animals injected, whereas only 20 % of the animals injected with the parental cell line expressing empty vector produced disease." (PMID 26384969, 2015). "Tumor tissue had a lower expression of RAB25 than normal tissue." (PMID 24403269, 2013). "Moreover, the last two studies showed that tumor samples underexpressed RAB25 as compared to normal tissue." (PMID 24403269, 2013). "Tumor tissue showed a lower expression of RAB25 than normal tissue." (PMID 24403269, 2013). "Published studies have shown that RAB25 could play a role as a tumor suppressor or as an oncogene depending on the cell type in which it is expressed." (PMID 24403269, 2013). "We compared RAB25 expression levels between 19 normal mucosa and 117 tumor samples." (PMID 24403269, 2013). "However, an opposite role of RAB25 has also been documented, i.e. as a tumor suppressor gene for colon cancer." (PMID 22724020, 2012). "We considered whether these conflicts in the literature may, in part, be explained by Rab25's capacity to elevate CLIC3 levels in the tumor in question." (PMID 22197222, 2012). "Rab25 has been reported to both promote and oppose tumor progression." (PMID 22197222, 2012). "There is also evidence that Rab25 can suppress tumor progression." (PMID 22197222, 2012). "Under these circumstances Rab25 will likely act as a tumor suppressor." (PMID 22197222, 2012). "Here we demonstrate a pathway for trafficking of activated α5β1 integrins in tumor cells that relies first on the ability of Rab25 to sort active heterodimers toward lysosomes, and then on CLIC3 to mediate the return of α5β1 from late endosomes/lysosomes to the cell surface." (PMID 22197222, 2012). "It was reported that RAB25 enhanced the ability of tumor cells to invade the extracellular matrix." (PMID 20142997, 2010). "Based on their different expression patterns among normal-tumor-thrombus triples, RAB25 and GGT5 were supposed to play a consistent role in both tumorigenesis and invasion processes, while SHMT2 and CADM4 might play the opposite roles in tumorigenesis and thrombus invasion." (PMID 37328520, 2023). "Importantly, we elucidated that tumor-derived exosomes-enriched miR-185-3p mediates tumor cell proliferation, colony formation, tumor growth, and drug response by targeting its downstream effector RAB25 that have potential therapeutic efficacy for HNSCC treatment." (PMID 34868916, 2021). "Interestingly, as a controversial factor, Rab25 serves as a tumor suppressor in colon cancer." (PMID 34440135, 2021). "Additionally, in colon cancer models, Rab25 exhibits a tumor suppressive function." (PMID 27259233, 2016).
tumor (continued). "The increased sensitivity to cisplatin and cell proliferation we observed in the UM-SCC-74B cell line overexpressing RAB25 could explain why patients with high-RAB25 tumor expression obtain greater clinical benefit from genotoxic treatment than patients with low RAB25 tumor expression." (PMID 24403269, 2013). "Also included in the gene set, but not further explored, was RAB25 encoding an epithelial-specific member of the Rab family of small GTPases, which can act as both a tumor enhancer and suppressor depending on the cellular context." (PMID 24216980, 2013). "However, by driving CLIC3 expression, Rab25 increases tumor aggressiveness." (PMID 22197222, 2012). "Another recent study indicated that Rab25 may function as a tumor suppressor in intestinal cells." (PMID 21143914, 2010). "In the case of RAB25 and EHF, both genes are well-known tumor suppressors that changed their methylation state." (PMID 37693315, 2023). "Combining the results of Wang’s and our own datasets revealed progressive downregulation of RAB25 and GGT5 from normal tissue to tumor to thrombus, suggesting their consistent suppressive roles in the development of both thrombi and tumors." (PMID 37328520, 2023). "RAB25 and GGT5 expression progressively decreased from normal tissue to tumor to thrombus, suggesting they consistently exert suppressive roles in both tumorigenesis and invasion." (PMID 37328520, 2023). "RAB25 is a small GTPases belongs to the member of RAB protein family and is a tumor suppressor in HNSCC." (PMID 34868916, 2021). "Consistent with the tumour volume data, the tumour tissue samples from the PC9/ER/shRab25 and HCC827/ER/shRab25 groups expressed lower Rab25, β1 integrin, β‐catenin and ki‐67 protein levels than those from the PC9/ER/shctrl and HCC827/ER/shctrl groups." (PMID 30848009, 2019). "Hypermethylation of the DNA promoter region for RAB25 has been reported previously, and both RAB25 and ESRP1 have tumor-suppressive effects." (PMID 26646320, 2016). "Mechanistically Rab25 decorated vesicles transport integrins, PI3K, and EGFR facilitating aggressive tumor growth and metastasis." (PMID 27259233, 2016). "Recently, the Rab25 and PTK6 genes were identified as tumor suppressors in ESCC, and these two genes were markedly down-regulated in ESCC tumorigenesis both in previous and in this study." (PMID 26158411, 2015). "The second connection including RAB25, SNAI1, and CDH1 was suggested to be related to tumor invasion." (PMID 20142997, 2010). "The connection including TGM2, IL1B, and PLAU and the connection including RAB25, SNAI1, and CDH1 were suggested to be related to tumor invasion by IPA." (PMID 20142997, 2010). "As previously reported that Rab25 acts as a tumor suppressor in the absence of CLIC3, whereas Rab25 increases tumor aggressiveness after driving CLIC3 expression." (PMID 38182571, 2024). "Tumor samples as well adjacent normal tissues (ANT) were acquired from fresh surgical specimens from 110 patients and the expression levels of let-7d, miR-185, Rab25, and snail were evaluated using real-time PCR." (PMID 33507713, 2021). "As a result, it is highly probable that Rab25 mediates erlotinib resistance by mediating the recycling of β1 integrin to the cytoplasmic membrane, which leads to AKT phosphorylation and subsequent downstream signalling to promote tumour cell proliferation." (PMID 30848009, 2019). "Moreover, mice injected with stable Rab25‐depleted cells (PC9/ER/shRab25 and HCC827/ER/shRab25) showed smaller tumour volumes than did the PC9/ER/shctrl‐ and HCC827/ER/shctrl‐injected mice." (PMID 30848009, 2019). "It is suggested that in the presence of CLIC3, Rab25 acts as an oncogene, whereas, in the absence of CLIC3, Rab25 acts as a tumor suppressor." (PMID 28969096, 2017). "Nevertheless, it was found that Rab25 regulates integrin recycling no matter when it acts as an oncogene or a tumor suppressor." (PMID 28969096, 2017).
tumor (continued). "Rab25 was discovered in tumours that did not respond to chemotherapy, implicating Rab25 as a potential oncogene regulating chemoresistance." (PMID 26384969, 2015). "Conversely, in tumors where Rab25 drives upregulation of CLIC3, lysosomally routed active integrins will be returned to the plasma membrane, thus avoiding degradation and enabling their continued signaling to drive tumor progression." (PMID 22197222, 2012). "The localization of S100P and RAB25 in tumor tissues was similar to that in cultured cells (data not shown)." (PMID 20142997, 2010). "The xenograft tumor sections were negative for RAB25 expression and showed overexpression of Snail." (PMID 38803515, 2024). "In addition, the downstream mechanisms activated by Rab25 when it acts as an oncogene or a tumor suppressor are not yet clear." (PMID 28969096, 2017). "The mechanisms that lead to the tumor suppressing function of Rab25 have not been fully understood." (PMID 28969096, 2017). "Notably, in this data set as well as other tumor databases, Rab25 and RCP expression are not always highly correlated." (PMID 27259233, 2016). "Further more, research has implicated that an important protein CLIC3 (chloride intracellular channel protein 3) may determine whether or not Rab25 acts as a tumor promoter or suppressor." (PMID 25815277, 2015). "Taken together, these data indicate that in the absence of CLIC3, Rab25 acts as a tumor suppressor." (PMID 22197222, 2012). "However, in tumors which contain a mosaic of cells with different phenotypes, EMT-mediated and specific RAB25-mediated migration could work in concert, with EMT-positive cells at the edge of the tumor leading the way for RAB25-positive epithelial cells cooperating to promote tumor progression." (PMID 30445998, 2018).
infection (4 papers, 2016 to 2020). The state of being infected such as from the introduction of a foreign agent such as serum, vaccine, antigenic substance or organism. "The result showed that the down-regulation of Rab25 expression significantly attenuated CSFV replication level at 48 h post-infection." (PMID 32114898, 2020). "At certain times after infection, the expression level of Rab25 was studied at mRNA and protein level." (PMID 32114898, 2020). "In particular, the mRNA expression of Rab25 was significantly induced by CSFV infection at 12 h post-infection." (PMID 32114898, 2020). "We therefore investigated the T3SS dependence of the distribution of clathrin endocytic (CHC, AP2-α, Rab5a and EEA1) and recycling [Rab11a, Rab11b, Rab25, Myosin 5b (Myo5b)] components upon EPEC infection of polarized MDCK cells." (PMID 31242273, 2019). "An unpublished screen of Rab-fusion proteins (data not shown) revealed that mCherry-Rab25 localises with high fidelity to the CTL2 inclusion throughout the infection." (PMID 26962046, 2016).
adenocarcinoma (1 paper, 2013). A common cancer characterized by the presence of malignant glandular cells. "In contrast, RAB25+/+ Smad 3+/− mice did not develop adenocarcinomas." (PMID 24403269, 2013).
RAB25 also shares sentences with these, for which no sentence is quoted: breast tumor (2 papers); clear cell renal cell carcinoma (2); cyst (2); dysplasia (1); glioblastoma multiforme (1); kidney tumors (1); liver cancer (1); mucinous adenocarcinoma (1); nasopharyngeal carcinoma (1); neurodegenerative disease (1); psoriasis (1); skin squamous cell carcinoma (1).